MRE11 (MRE11 double strand break repair nuclease)
Diseases named in the same sentence as MRE11 in open-access papers (continued):
Sharing a sentence is not in itself a finding about the gene and the disease.
cancer (continued). "In conclusion, our study first reveal that elevated MRE11 expression is significantly correlated with cancer progression and poor survival in PCa patients." (PMID 31413753, 2019). "In our analysis, we found that seven out of 10 pedigrees had potential co-segregated pathogenic variants in known cancer-associated genes, including CHEK2, ATM, MRE11, and CTR9, and some other cancer-associated genes, such as IGF2R and CHRNA3." (PMID 31214250, 2019). "As a result, it was of high importance to explore MRE11 expression and cancer survival in relation to other factors that affect the clinicopathological significance in CRC, such as microsatellite instability (MSI)." (PMID 32010608, 2019). "Active ATM monomers phosphorylate H2AX, which triggers NHEJ, and phosphorylate some nucleases, like MRE11, which inactivates the MRE11-dependent recombination-like DSB repair pathway responsible for cancer proneness or genomic instability." (PMID 31261657, 2019). "Derivatives of mirin have been used for the studies of MRE11 endonuclease and exonuclease, while their potential function in cancer treatment remains poorly explored." (PMID 31767017, 2019). "Preclinical trials of ATR inhibitors have demonstrated anti-tumour effects in cancer cells with low MRE11 expression." (PMID 30769804, 2019). "Intriguingly, cancer prone mutations in SAMHD1, which is required for replication fork stability and regulation of Mre11-dependent degradation of nascent DNA, activate the IFNγ pathway promoting cancer development." (PMID 29950452, 2018). "They found that Zscan4c co-operates with Rad50 and Mre11 to maintain the telomere length by homologous recombination as found in some cancer cells." (PMID 25772165, 2015). "However, in radiation-treated cancer cells, excessive MRE11 cleavage instead increases radiation sensitivity." (PMID 39759116, 2025). "High MRE11 Kla level promotes homologous recombination and chemoresistance in cancer cells." (PMID 40563450, 2025). "Additionally, increased expression of MRE11 in certain cancer types has been illustrated in patients undergoing irradiation therapy." (PMID 40001488, 2025). "Notably, this list of MRE11 phosphorylation sites in cancers contains Thr597 and Ser619, which we identified in this study to be phosphorylated by the kinase PKB." (PMID 40479710, 2025). "However, in cancer cells subjected to radiotherapy, MRE11 is recruited to the damage site to cleave damaged dsDNA to produce ssDNA for HR repair." (PMID 39759116, 2025). "Therefore, the over-cleavage of MRE11 is a double-edged sword, and its rational utilization will likely be a potential target for cancer therapy." (PMID 39759116, 2025). "Collectively, these data indicate that targeting MRE11 K673 lactylation with K673-pe could enhance chemotherapy efficacy in cancer with high MRE11 K673 lactylation." (PMID 39872378, 2024). "We assessed the prevalence of post-replicative gaps in cancer cells deficient in MRNIP, an MRE11 interactor that suppresses MRE11 exonuclease activity in vitro, and which prevents MRE11-dependent degradation of nascent DNA at stalled, reversed replication forks." (PMID 38917325, 2024). "The absence of correlation between ERR and both MRE11 and global nuclease activity assays also demonstrated that the nuclease step alone is not predictive of cancer risk/proneness." (PMID 39335159, 2024). "The data show that MRE11 may be a biomarker of response to RT and its altered expression correlates with radiosensitivity in cancer." (PMID 37894339, 2023). "These resultsalso raised a question about a possible resistance mechanism to POLθinhibitors in HR-defective cancer cells with nonlethal cancer mutationsin Mre11-Nbs1-CtIP genes." (PMID 37134182, 2023).
cancer (continued). "We conclude that MRE11 is an attractive anti-cancer target and that the pharmaceutical development of MRE11 inhibitors for precision oncology therapeutics may have clinical benefit." (PMID 37446144, 2023). "However, the final cancer transformation appears to be dependent on the concomitant alteration of the Ink4a/Arf gene, which is favored in Mre11 mutants." (PMID 37754262, 2023). "Furthermore, we find that cancer-related MRE11 mutants exhibit both ectopic SUMOylation and compromised DNA end resection ability." (PMID 36050397, 2022). "As MRE11 and NBS1 deficiencies sensitize human cancer cells to etoposide, it is worth investigating combination with etoposide and the MRE11 endonuclease inhibitors (PFM 01 and 03) in cancer cell lines as well as tumor xenograft models with different MRE11 expressions." (PMID 36213114, 2022). "In our study, we also explored the connections between MRE11 SUMOylation and cancers." (PMID 36050397, 2022). "However, further mechanistic studies will be required to confirm the clinical implication of mitochondrial Mre11 in cancer cells." (PMID 35853939, 2022). "Additionally, polymorphisms in predicted miRNA target sites of MRE11, NBS1, RAD51 and RAD52 have been associated with different cancer risks, susceptibility, and survival." (PMID 35328651, 2022). "Cancer cells rely on DNA repair for survival during cancer therapies, and thus MRE11 might be a promising synergistic therapeutic target." (PMID 35875060, 2022). "This raised a hypothesis that the oncogenic effect of MRE11 on OSCC may involve the enhancement of cancer stemness." (PMID 35629265, 2022). "We found that cancer-related MRE11 K255E and K384Q mutants were prone to degradation after treatment with DSB-inducing agents, which led to failed DNA end resection and thus may result in genome instability and tumorigenesis." (PMID 36050397, 2022). "Finally, our analysis of DEGs associated with low expression of MRE11, RAD50 and NBS1 identified increased expression of seven genes associated with mitochondrial dysfunction and metabolic reprogramming in cancer." (PMID 34782604, 2021). "Furthermore, MRE11 is supposed as a potential target for cancer therapy, since inhibitors to MRE11 exhibited promising therapeutic effects in cancer cells, either as favorable sensitizers or antitumor agents." (PMID 34440334, 2021). "Moreover, evaluation of the Reverse Phase Protein Array (RPPA) data set from the Cancer Cell Line Encyclopedia (CCLE) showed that MRE11, a component of the MRN complex, was highly expressed at the protein level in radioresistant SCLC cells." (PMID 33632300, 2021). "In humans, mutation of Mre11 can cause ataxia-type telangiectasia-like disease (ATLD), which is characterized by chromosomal instability, radiation hypersensitivity, neurological deficits, and susceptibility to certain types of cancer." (PMID 33375295, 2020). "Due to its essential role in limiting the deleterious effect of RS in MYCN-driven cancer cells, MRE11 might represent a novel therapeutic target for MYCN-driven tumors." (PMID 30166519, 2018). "NBN is DNA repair family gene, involved in the MRE11/RAD50/NBN complex, with nine variants (rs1805794, rs1805790, rs36226237, rs924, rs376639, rs1061302, rs1063054, rs2735383, rs805794) described as associated with high cancer risk." (PMID 28402931, 2017). "We can theorize that the modulatory role by the observed SNP on the expression of MRE11 protein may also influence the prognosis of cancer." (PMID 26735576, 2016).
cancer (continued). "For example, high MRE11 expression specifically predicts improved outcome with radiotherapy, demonstrating 16% improvement in 3-year cancer-specific survival (CSS) compared with high MRE11 expression treated with cystectomy (69.9% vs 53.8% 3-year CSS, P=0.021)." (PMID 25897675, 2015). "To date, the association of the molecular variants in the RAD50 and MRE11 gene with the cancer risk has not been so extensively studied." (PMID 24093751, 2013). "Indeed, MRE11 mRNA and protein are overexpressed in most types of cancer." (PMID 41193733, 2025). "Notably, MRE11's role varies across cancer types, warranting further mechanistic clarification." (PMID 40963916, 2025). "Biallelic loss of HRR genes, especially BRCA1, BRCA2, RAD51D, RAD51 C, and PPP2R2 A was linked to higher HRD scores in BRCA-associated cancers, while BARD1, RAD51D, RAD54L, BRCA1, and MRE11 were associated with elevated HRD scores in in other cancer types (non-BRCA cancers)." (PMID 40420266, 2025). "However, the development of a bioconjugate charged with Mre11 inhibitors represents a concrete opportunity for the targeted delivery of these molecules that could find application in therapy even beyond cancer, being involved also in viral infections." (PMID 39341955, 2024). "Furthermore, a large subset of cancer syndromes tested here are associated with the absence of MRE11 foci or an unusual shape of MRE11 foci: this is the case of the BS, FANC, NBS, and ATM cells, in agreement with the literature." (PMID 39335159, 2024). "This is also the first report demonstrating the association of MRE11 rs2155209, XRCC5 rs828907, LIG4 rs1805388, ATM rs1801516 and RAD51 rs12593359 with survival in HNSCC, as well as the first to indicate that CHEK1 rs558351 may play a role in cancer disease." (PMID 37894339, 2023). "Moreover, the somatic mutational spectra in MRE11, RAD50, and NBS1 can influence cancer phenotypes." (PMID 37446144, 2023). "In our results, these MRE11 data suggest both the presence of some early misrepaired DNA strand breaks that might reflect a cancer-prone hyper-recombination process, and the accumulation of some late DNA strand breaks that are generally associated with an aging phenotype." (PMID 35163494, 2022). "Interestingly, no mutations within the MRE11 gene were identified in the 585 samples (TCGA Pan Cancer cohort)." (PMID 35853939, 2022). "Having identified the Rad50L1237F mutation as the underlying cause of an extraordinary response to chemotherapy, likely due to its selective inability to activate Tel1/ATM, we reasoned that cancer genomic data could offer a rich source for understanding Mre11 complex functions." (PMID 32187176, 2020). "Interestingly a persistent non-random level of TUNEL and TUNEL-associated MRE11 and Ku existed within undamaged cells, possibly due to genuine endogenous levels of genomic stress which are known to be elevated in cancer cells." (PMID 33370257, 2020). "Also, the endonuclease and exonuclease function of MRE11 complicates its role in cancer." (PMID 31767017, 2019). "Mutations in ATM (Ataxia Telangiectasia Mutated), MRE11, NBS1 (Nijmegen Breakage Syndrome), BRCA1 (Breast Cancer 1), BRCA2 and Ligase 4 cause human syndromes characterized by both CABs and cancer predisposition, highlighting the connection between CABs and cancer." (PMID 24651653, 2014). "Therefore, the common DNA damage phenotypes of the replisome mutants described here could explain the SL relationship with cancer CIN genes involved in DNA repair (MRE11/SGS1) and the cell cycle (BUB1)." (PMID 23390603, 2013). "When WRN nuclease activity is inhibited, MRE11 will cleave unprotected forks, generating mus81-dependent DSBs, while increasing NHEJ and chromosomal instability, leading to cancer cell death." (PMID 39759116, 2025).
cancer (continued). "Indeed, it was shown that MSI cancer cells could no longer efficiently repair DSBs in the context of splice-altering mutations in the ATM gene or in the MRE11 gene from the MNR (MRE11/NBS1/RAD50) DNA mutation repair system." (PMID 36833239, 2023). "Most notably, racial differences between Black and White samples in the expression of genes pertaining to homology-directed repair, including RAD50, RAD51, MRE11, ERCC1, and BRCA2, were observed in five cancer types." (PMID 37345032, 2023). "MRE11, RAD50, and NBS1 expressions as clinical biomarkers for cancer prognosis and responses to chemotherapies have been reported." (PMID 36213114, 2022). "While our current study provided evidence to reveal a novel pathway linking MRE11 and OSCC malignancy through enhancement of cancer stemness, there are also limitations in the interpretation of our data, and study areas to be further investigated." (PMID 35629265, 2022). "In this study, we aimed to investigate the engagement of CD44, a cancer stemness marker functioning in the control of cell growth and motility, in OSCC malignancy under the influence of MRE11." (PMID 35629265, 2022). "Human cancer cells use both proteasome‐dependent and proteasome‐independent endonucleolytic pathways (TDP1, PARP1, XPF‐ERCC1, MRE11, CTIP, and MUS81‐EM1) to remove TOP1cc." (PMID 35582959, 2022). "On the other hand, MRE11, RAD50 and NBS1 protein components of the MRN complex are often overexpressed and sometimes essential in cancer." (PMID 35839783, 2022). "C1QBP stabilizes the MRE11 protein by forming an MRC complex with MRE11/RAD50 and inhibiting MRE11 exonuclease activity, thereby demonstrating that C1QBP plays a crucial role in the DNA damage response and serves as a potential target for cancer therapeutics." (PMID 33708767, 2021). "In MRE11-overexpressing cells, RNA expression of CXCR4, a cell membrane protein involved in cancer cell migration and invasion, was increased, but this was reversed when cells were cotreated with siCXCR4." (PMID 33927349, 2021). "The HR pathway is initiated by MRE11, RAD50, and NBS1 a complex termed MRN (Inhibiting homologous recombination for cancer therapy)." (PMID 34199757, 2021). "In breast cancer cells, overexpression of MRE11 leads to cell proliferation by stimulating the STAT3 signaling pathway, and enhances the migration and invasion of cancer cells via activation of MMP-2 and MMP-9." (PMID 34440334, 2021). "To test if this effect was dependent on MRE11, we determined the effect of KD of RECQL on DNA DSB formation in the presence of Mirin for two cancer cell lines." (PMID 32820027, 2020). "Relationship between MRE11 and PCa was rarely documented, while it is noteworthy that MRE11 is a confirmed repair factor in DSB response process and estimated highly expressed in many cancer patients." (PMID 31413753, 2019). "In line with this, we have now demonstrated that MRE11 is also required for an efficient RS control and for the survival of preclinical models of established MYCN-driven human cancer." (PMID 30166519, 2018). "Together with the radiosensitivity index, MRE11 has been the most studied MRN complex component, and its prognostic value has been assessed in different cancers, including CRC." (PMID 29189711, 2017). "Immunohistochemical analysis of MRE11, RAD50 and NBS1 was successful in a maximum of 134 carcinomas." (PMID 28073364, 2017). "Vorinostat was additionally found to suppress the DNA repair proteins, RAD50 and MRE11, in cancer cells and not normal cells, collectively resulting in cancer cell death." (PMID 40011240, 2025). "Moreover, considering that the cytotoxic agent is an Mre11 inhibitor, our findings also indicate this strategy as a promising opportunity for a renewed application of DDR inhibitors in cancer therapy." (PMID 39341955, 2024).
cancer (continued). "According to this concept, restraining PARP1 could be a latent therapeutic schedule for the therapy of cancers with defects in precise DNA repair genes, such as XRCC2, MRE11, and BRCA1/2." (PMID 38907095, 2024). "In papillary thyroid carcinoma (PTC), the downregulation of MRE11 and RAD50 expression, through the lncRNA SLC26A4-AS1-mediated disruption of the DDX5-E2F1 transcription factor complex, inhibits the invasion and metastasis capability of cancer cells." (PMID 37509263, 2023). "Inverted duplications, also known as foldback inversions, are commonly observed in cancers and are the major class of chromosome rearrangement recovered from yeast cells lacking Mre11 nuclease activity." (PMID 37919272, 2023). "Biomarker analysis has suggested that DNA damage response markers, such as MRE11 and ERCC1/2, may predict cancer-specific survival among two independent TMT cohorts." (PMID 37641150, 2023). "MtrBTN2 cancer was found to express at higher levels a significant panel of transcripts of genes involved in the DNA homologous recombination (HR) (42.Double-strand break repair), such as BABAM1, ZSWIM7, RAD51L, RAD54L, MRE11, MCM9 and TONSL." (PMID 37816387, 2023). "As developed in Section 3.5, in the frame of the RIANS model, abnormal MRE11 activity and abnormal MRE11 foci kinetics appear to be correlated to the hyper-recombination phenomenon and cancer proneness, but not necessarily to toxicity." (PMID 34680095, 2021). "Because our results suggested that RECQL protects against MRE11-dependent DNA DSB formation, we hypothesized that RECQL is essential in cancer cells suffering from replication stress to prevent replication fork collapse." (PMID 32820027, 2020). "This suggests that also in human cancer cells, RECQL prevents MRE11-dependent DNA DSB formation." (PMID 32820027, 2020). "Moreover, several other compounds targeting proteins involved in DNA repair mechanisms have already shown promising results as potential new anti-cancer drugs in pre-clinical studies, such as BLM, WRN, RAD52, or MRE11 inhibitors." (PMID 33036275, 2020). "The MRE11/RAD50/NBS1 (MRN) complex plays an essential role in detecting and repairing double-stranded breaks, and thus the potential roles of MRE11, RAD50 and NBS1 proteins in the pathogenesis of various cancers is the subject of investigation." (PMID 30176843, 2018). "Additionally, the authors showed that vorinostat suppressed the DNA repair proteins, MRE11 and RAD50, in only the cancer cells, collectively leading to cancer cell death." (PMID 29651407, 2018). "Interestingly, the selective inhibition of Mre11 is reported to increase cancer sensitivity to radio- and chemotherapy, being not compatible with cell survival, and raised attention around this target for precision oncology therapies." (PMID 39341955, 2024). "Because both the ATM and MRE11 genes, which as act as players in the MNR (MRE11/NBS1 (Nibrin)/RAD50 (RAD50 double strand break repair protein) DNA damage repair system, participate in double strand breaks (DSB) repair, their frequent splicing alterations in MSI cancers lead to impaired activity." (PMID 36833239, 2023). "Furthermore, SPRTN levels were not significantly correlated with MRE11 levels and were independent of cancer stage." (PMID 33558481, 2021). "The potential role of the MRE11 gene in human cancers is not well documented." (PMID 24079363, 2013). "Thus, MRE11 recruitment in HAP-1 cells without external replication stress feasibly could be a reflection of increased intrinsic replication stress in cancer cells compared with primary cells, or alternatively differences between species." (PMID 29475976, 2018). "Interestingly, an early increase in the number of MRE11 foci revealing DNA strand break sites that are not managed by NHEJ has been correlated with the hyper-recombination process and cancer-proneness." (PMID 34680095, 2021).